BMP2 (bone morphogenetic protein 2)
Diseases named in the same sentence as BMP2 in open-access papers (continued):
Sharing a sentence is not in itself a finding about the gene and the disease.
tumor (continued). "A recent large systematic review by Skovrlj et al30 found no studies that demonstrated BMP-2 use causing cancer de novo but did find 43% of included studies, suggesting that BMP-2 enhances tumor function." (PMID 39392937, 2024). "The encapsulation of cisplatin and BMP-2 into pZIF-8 resulted in drug delivery that was triggered by the tumor microenvironment." (PMID 39601916, 2024). "Bioinformatic analyses indicate that BMP signaling pathway activation ground state is independent of ACVR1 status in pDMG, which likely results both from BMP2/7 tumor-autonomous and microenvironment-driven signals in ACVR1 WT tumors." (PMID 39373720, 2024). "According to previous studies, BMP2 significantly inhibits tumor cell proliferation and induces cancer cell autophagy and differentiation." (PMID 38672212, 2024). "BMP2 is highly overexpressed in nonsmall cell lung cancer (NSCLC) and associated with tumor staging and metastasis." (PMID 38610001, 2024). "In CRC primary tumours, the hypermethylation of bone morphogenetic protein 2 (BMP2), cyclin-dependent kinase inhibitor 2A (CDKN2A), and family with sequence similarity 134 member B (FAM134B) was associated with lymph node metastases." (PMID 38255946, 2024). "BMP2 significantly increases the migration of tumor cells from Matrigel-embedded 3D-DIPG spheroids, while an antagonistic effect was observed upon LDN treatment." (PMID 39373720, 2024). "We found that the level of protein expression of BMP2 in the tumor tissues of mice in the knockdown group was lower than that in tissues of mice in the normal group, as indicated by WB." (PMID 38610001, 2024). "Second, genetic, environmental, and lifestyle differences affect tumor behavior; therefore, the applicability of BMP2 as a biomarker in different populations needs to be further validated." (PMID 38610001, 2024). "BMP2 is a multifaceted gene that can exhibit both tumor-promoting and tumor-suppressive effects in different types of cancers." (PMID 38378721, 2024). "It was concluded that (i) BMP-2 is capable of initiating and inducing breast MCs, and (ii) tumor growth is exponential over the 5 weeks of monitoring." (PMID 39590935, 2024). "CD34/PAS staining showed that after BMP2 knockdown, the number of formed VMs within the tumor was significantly decreased." (PMID 38610001, 2024). "The most recent research results have revealed that the promotion of epithelial mesenchymal transition (EMT) and enhancement of tumor cells’ metastatic capability are facilitated by BMP2." (PMID 38059889, 2023). "The xenografted tumors in both groups were utilized for IHC analysis, and the level of BMP2 expression was significantly high in tumor tissues of the circEPHA3 overexpressing group." (PMID 37118847, 2023). "In line with prior discoveries, the expression of BMP2 in PC samples was found to be significantly elevated compared to non-tumor PC tissues." (PMID 38059889, 2023). "In a patient-derived xenograft model, IRDye800cw-labelled C4C4 and C8C8 effectively target BMP4 and BMP2/4, respectively, and inhibit tumor growth." (PMID 37746282, 2023). "Mechanistically, circEPHA3 was directly bound to miR-513a-3p and regulated the downstream gene, BMP2, thereby serving as a tumor suppressor in PCa." (PMID 37118847, 2023). "Large quantities of bone morphogenetic protein 2 (BMP-2) and tumor necrosis factor β2 (TGF-β2) are secreted during the neutrophil invasion of the tumor microenvironment, which causes microRNA-301-3p expression in HCC cells." (PMID 36761433, 2023). "TAMs, as an important component of the tumor microenvironment, were found to be able to secrete BMP-2 that contributes to vascular calcification." (PMID 34983451, 2022). "Bone morphogenetic protein 2 (BMP-2) was strongly expressed in tumor cells and weakly expressed in the stromal cells around the HO." (PMID 36415832, 2022).
tumor (continued). "Using IHC, we confirmed the presence of SHH in both stromal and cancer cells of EAC, while BMP2 and 4 were mostly expressed in the cytoplasm of the tumor cells." (PMID 35902550, 2022). "Reduction of Bmp2 expression is consistent with the tumor suppressive role of BMP signaling in the ovarian GCT formation." (PMID 35565312, 2022). "Similarly, Zhou S 41 proved that tumor-associated neutrophils could secret BMP-2 and TGF-β2, which triggered the expression of miR-301b-3p through paracrine and further induced the activation of NF-κB signaling, finally increasing stem cell characteristics in HCC cells in vitro." (PMID 34975338, 2022). "Similar to TRPM8, the untreated animals showed an upregulation of BMP2 positivity staining within tumour regions." (PMID 34910361, 2022). "In the same vein, GDF-15, in combination with BMP-2, has been shown to mediate the inhibition of fenretidine-dependent tumor vessel growth by interfering with endothelial cell growth, migration, and invasion." (PMID 33790859, 2021). "Immunohistochemical analysis showed tumor cells positive for BMP-2, osteonectin, osteocalcin, AE1/AE3, TGF-β1, Gli2, Smad2/3, and CDX2 and negative for nestin, CD56, and CK7." (PMID 33388078, 2021). "In addition, in line with the current consensus, although an overdose of BMP-2 could lead to over-proliferation of cells, which may increase the risk of neoplasm formation and tumorigenesis, using a low dose and a slow-release delivery pattern of BMP-2 appears safe for oncogenesis-related research." (PMID 34869325, 2021). "BMP-2 also acts as both a tumor suppressor and oncogenic factor, and endogenous BMP has been shown to be increased in cancers and metaplastic bone formation." (PMID 35463995, 2021). "Chronic exposure of human immature mammary cells to high BMP2 levels initiates SC transformation toward a luminal tumor phenotype." (PMID 35047500, 2021). "Transforming growth factor-beta 1(TGF-β1) and BMP-2 are members of the transforming growth factor-beta family, which exert important roles in tumor growth and invasion." (PMID 34221185, 2021). "The BMP-2 signaling pathway enhances tumor metastasis in GC via sequential activation of the PI3K/AKT or MAPK pathway activation." (PMID 34001012, 2021). "TrkC blocks the BMP tumor suppressor activity through the suppression of bone morphogenetic protein 2 (BMP-2)-induced Smad1 phosphorylation and transcriptional activation by directly interacting with the BMP type II receptor." (PMID 31936239, 2020). "Both H22 and Hepa1-6 tumor volumes and tumor weights were compared between the control and the BMP2 group." (PMID 32195173, 2020). "Quantitation of IHC staining between NPC tumours and normal nasal epithelium revealed average intensity scores of 6.1 versus 3.6 (p-value < 0.0001) for BMP2, and 7.7 versus 4.4 (p-value < 0.001) for pSmad1." (PMID 32708289, 2020). "Tumor-activated neutrophils release BMP2 to trigger the expression of miR-301-3p in HCC cells, which down-regulates LSAMP and CYLD expression to increase the stemness of HCC cells." (PMID 32632106, 2020). "We have shown that chronic exposure to high concentrations of BMP2 drives the transformation of mammary SCs toward the luminal tumor subtype through the binding to its BMPR1B receptor." (PMID 31547326, 2019). "Previous studies have shown that SPP2 inhibits the growth of tumor cells in prostate cancer, pancreatic cancer and hepatocellular carcinoma and attenuates the growth-enhancing effects of BMP2." (PMID 31849319, 2019). "They concluded that addition of BMP-2 results in inhibition of tumor-inducing gene expression and an upregulation of osteogenic differentiation markers." (PMID 28264040, 2017). "We saw differential expression of BMP2 and BMP4 ligands in all tumour subtypes, with downregulation of BMP2 and upregulation of BMP4 expression as compared with normal colon." (PMID 28299802, 2017).
tumor (continued). "Both the in vitro experiments and the clinical evidence support that BMP2 over-expression promotes tumor proliferation and aggressiveness of NPC." (PMID 28455969, 2017). "Collectively, these findings support that BMP2 promote tumor proliferation and invasion via activation of mTORC1 signalling pathway in NPC cells." (PMID 28455969, 2017). "Studies have focused on the effects of BMP-2, which has a direct anti-proliferative effect on tumour cells at a very high concentration in vitro." (PMID 28733469, 2017). "The result showed that the expression of BMP2 was significantly up-regulated in tumor tissues compared with non-tumor tissues (P<0.01)." (PMID 28455969, 2017). "For example, Smad1 can be induced by many tumor-stimulating cytokines such as the bone morphogenetic protein 2 (BMP2) and TNFα and plays important roles in cell invasion and metastasis." (PMID 29299158, 2017). "We previously demonstrated that CA-MSCs significantly promote tumor growth in a BMP2/4-dependent manner." (PMID 26755648, 2016). "Calcitriol epigenetically regulates tumor-related genes (i.e., bone morphogenetic protein-2, BMP-2) through DNA methylation and histone modifications." (PMID 27973439, 2016). "Most recently, it has been reported that BMP-2 inhibits tumor growth in human RCC and induces bone formation." (PMID 27891093, 2016). "Bone Morphogenic Protein 2 (BMP2) is a multipurpose cytokine, important in the development of bone and cartilage, and with a role in tumour initiation and progression." (PMID 27114889, 2016). "As one branch of BMPs, BMP-2 also has important effects on tumor’s proliferation, invasion and angiogenesis." (PMID 27886213, 2016). "Anti-BMP2/4 antibody significantly suppressed xenografted tumor growth induced by Dragon overexpression." (PMID 26029998, 2015). "Coupled with the changes in tumor sizes, Smad1/5/8 phosphorylation induced by Dragon in tumor tissues at day 22 was inhibited by anti-BMP2/4 antibody." (PMID 26029998, 2015). "In summary, our findings show that BMP-2 is an important tumor suppressor that is down-regulated by promoter CpG hypermethylation in RCC." (PMID 25797254, 2015). "BMP-2 is thought to be a putative tumor-suppressor gene in several types of cancer (i.e., gastric, colon, prostate, adrenal)." (PMID 25797254, 2015). "To date, several studies have shown that BMP-2 inhibits the growth of tumor cells in various types of cancer including RCC." (PMID 25797254, 2015). "When these variables were subjected to a multivariate model, BMP-2 expression and tumor stage were shown to be significantly independent predictors for OS after a radical nephrectomy." (PMID 25797254, 2015). "The potential off-label risks of BMP-2 have been documented in the literature and include: ectopic bone formation, swelling/hematoma, neoplasia, and wound problems; this should be taken into consideration when using these therapies off-label." (PMID 25298784, 2014). "Persano and coworkers found that BMP2 was not only an effective prodifferentiation treatment for GBM-derived stem cells but also that the BMP2-mediated differentiation made the tumor cells more sensitive to Temozolomide (TMZ) treatment." (PMID 24877113, 2014). "Here, we investigated the effect of BMP2 on the proliferation, migration, invasiveness and tumor growth capability of human CRC cells." (PMID 24993644, 2014). "Using a xenograft tumor model, we found that forced expression of BMP2 in HCT116 cells suppressed tumor growth, accompanied by decreased cell proliferation activity." (PMID 24993644, 2014). "Using a xenograft tumor model, we found that forced expression of BMP2 in HCT116 cells suppressed tumor growth, accompanied by decreased proliferative activity." (PMID 24993644, 2014). "This, together with the crucial role of BMP2 in oncogenic transformation and tumour angiogenesis, suggests that the p55γ/p110α complex positively regulates BMP2-induced motility, chemotaxis, and invasion of endothelial and cancer cells." (PMID 24885555, 2014).
tumor (continued). "Even BMP2 and activin, members of the TGFβ superfamily and pleiotropic cytokines that also exhibit tumor promoter and suppressor activities, had little effect on CD248 expression." (PMID 24555435, 2014). "Previous studies of BMP-2 have focused on the expression of BMP-2 in tumor tissues and its function in tumor cell proliferation, invasion, and migration." (PMID 24946687, 2014). "We reported that the TGF-β family member BMP-2 is a mediator of the antiangiogenic activity of 4HPR, controlling tumor growth." (PMID 20537156, 2010). "BMP-2 plays an important physiological role in various tissues throughout the body and has been shown to be expressed in tumor tissues." (PMID 20587070, 2010). "MYC, BMP2, and FOS show an associative trend when overexpressed, and TNFRSF10A shows a trend in underexpression in the tumor cohort." (PMID 20465837, 2010). "Here we depict the molecular mechanisms occurring in normal and tumor cells after high oxygen tension acute exposure and BMP2 treatment." (PMID 19587783, 2009). "More than half of the patients tested showed higher expression of BMP-2 in tumor cells from ascites compared to tumor cells from solid tumors." (PMID 19366455, 2009). "In normal SVZ cells Akt, mTOR and its downstream targets were only transiently modulated by BMP2, indicating a different sensitivity between tumor and normal cells in responsiveness to exogenous BMP2." (PMID 19587783, 2009). "On the other hand, BMP-2 clearly inhibits the growth of tumor cells of many origins including cancers arising from thyroid, androgen-dependent prostate in presence of androgen, myeloma, gastric and pancreatic cells." (PMID 19366455, 2009). "In contrast, when expressed in NOSE tissues, the expression of BMP-2 was globally weaker than in tumour tissues." (PMID 16421595, 2006). "We also tested the expression of TNFR1 and BMP-2, two upregulated genes in tumour ascites cells relative to NOSE samples." (PMID 16421595, 2006). "In contrast, another recent study demonstrated the ability of BMP-2 to enhance the growth of tumours." (PMID 16001974, 2005). "A study realised on cerebellar primitive neurectodermal tumor cell line demonstrated that a high concentration of BMP2 and BMP4 attenuate apoptosis." (PMID 15369599, 2004). "Interestingly, the expression of BMP-2 from either the primary tumor or adjacent stroma varies from case to case." (PMID 41523983, 2026). "Furthermore, we extracted proteins from tumor tissues and performed Western blot analysis to examine the expression level of BMP2." (PMID 40297808, 2025). "Our findings showed that the level of H19 in tumor tissues was negatively correlated with hsa-miR-138-5p and hsa-miR-22-3p (r = -0.50, P = 0.03; r = -0.55, P = 0.01), while H19 was positively correlated with BMP2 mRNA expression (r = 0.98, P < 0.001)." (PMID 40297808, 2025). "Alternatively, BMP2 expression may be a failed compensatory attempt at differentiation that is overridden by tumor-intrinsic resistance mechanisms or epigenetic silencing of downstream effectors." (PMID 40869118, 2025). "Proposed mechanisms involve tumor-induced osteogenic angiogenesis mediated by BMP-2/VEGF crosstalk." (PMID 40260301, 2025). "A comprehensive understanding of the mechanistic role of BMP2 in breast MCA could enhance our understanding of tumor biology and facilitate the development of novel therapeutic strategies, with a potential to improve clinical outcomes in this rare tumor type." (PMID 40936753, 2025). "These complexities highlight the need for mechanistic studies at single-cell or spatial resolution to delineate whether BMP2 exerts tumor-promoting or tumor-suppressive effects in different tumor compartments or stages." (PMID 40869118, 2025). "Reconstruction following tumor resection does not rule out the risk of the carcinogenic potential associated with substances, such as bone morphogenetic protein-2 (BMP-2)." (PMID 39335226, 2024). "(D) Impact of BMP2 or LDN treatment on tumor cells invasion." (PMID 39373720, 2024).
tumor (continued). "More specifically, under weakly acidic conditions and high H2O2 concentrations, the scaffold released cisplatin and BMP-2 to inhibit tumor growth and accelerate osteogenic differentiation, further enabling new bone formation through the acid/H2O2-induced cleavage of pZIF-8." (PMID 39601916, 2024). "BMP-2 inhibits the tumor-initiating ability of renal CSCs and promotes bone formation in vivo." (PMID 37685983, 2023). "As a tumor suppressor, circEPHA3 inhibited the proliferation and metastasis of PCa cells through the miR-513a-3p/BMP2 axis, suggesting that circEPHA3 might be a potential therapeutic target for PCa." (PMID 37118847, 2023). "Depending on the cancer type, BMP-2 has been shown to either drive or prevent tumor growth." (PMID 37685983, 2023). "BMP2 contributes to tumor cell migration, invasiveness and metastasis." (PMID 35902550, 2022). "Furthermore, tumor cells acquire the ability to express and secrete BMP-2 and TGF-β1, contributing to the transformation of fibroblasts and pluripotent stem cells into bone cells." (PMID 36415832, 2022). "Similarly, suppressed BMP2 in HepG2 cells inhibits tumor development, progression, and angiogenesis in HCC via inactivating the MAPK/p38 signaling pathway." (PMID 35573701, 2022). "To further investigate whether inhibition of BMP4 and BMP2/4 in SMAD4(-) ISO76A cells could attenuate tumor growth and potentiate the effect of cisplatin in the PDX model, we compared the effects of C8C8 and C4C4 with and without cisplatin treatment in vivo." (PMID 35902550, 2022). "Macrophages, acting as both immune cells and osteoclast precursors, are one of the major immune cells in the tumor microenvironment, and have been demonstrated to have the ability to secrete osteoinductive signals including BMP-2, which plays important role in osteogenesis." (PMID 34983451, 2022). "To explain why BMP2 expression levels in cancer cells did not correlate with prognosis, we have to consider tumor microenvironment, which are composed of cancer-associated fibroblasts that support tumor epithelial growth, invasion, and therapeutic resistance." (PMID 36175474, 2022). "Given the roles of BMSCs in the origination of OS and osteogenesis, we hypothesized that the responses of BMSCs to BMP-2 in the tumor milieu may be responsible for OS development." (PMID 34869325, 2021). "The presence of TGF-β1 in tumor cells demonstrated by immunohistochemistry suggests that tumor cells secrete this factor into the microenvironment, which might, much like BMP-2, stimulate pluripotent stromal cells or fibroblasts to transform into osteocytes." (PMID 33388078, 2021). "BMP-2 may promote OS progression through modulation of the tumor microenvironment (TME), which plays an indispensable role in tumor progression." (PMID 34869325, 2021). "The mean tumor size in the hMSCs group was significantly greater than that of the controls (p < 0.01).The extent of the tumoral necrotic area was found to be significantly more in hMSCs (p < 0.001) and BMP2+hMSCs (p < 0.05) groups compared to the others." (PMID 34377054, 2021). "Alternatively, the amount of hMSCs in the tumor environment might be more than the amount that could be compensated by the released amount of BMP2 for a sufficient suppression of the metastatic process." (PMID 34377054, 2021). "Our results suggest that TrkB expression might enhance the tumorigenic potential of the tumor by countering BMP-2-mediated growth inhibition." (PMID 32731498, 2020). "Furthermore, the infiltration of MDSCs and the activation of BMP2 signaling in tumor tissues were detected by immunofluorescence staining." (PMID 32195173, 2020). "In our mouse models, high concentration of BMP2 within the peripheral blood could promote the differentiation of MDSCs from bone marrows and the infiltration of MDSCs to tumor tissues." (PMID 32195173, 2020).